PAX5 (paired box 5)
Diseases named in the same sentence as PAX5 in open-access papers (continued):
Sharing a sentence is not in itself a finding about the gene and the disease.
cancer (continued). "Although biomarkers related to cancer are well studied, autoantibodies to PAX5, PTCH1, and GNA11 were reported in a previous study where their existence and specificity among different ethnic populations were underreported." (PMID 36835134, 2023). "Further, in hematopoietic tumors, Pax5 seemed to regulate the myeloid versus B cell lineage phenotypes in the cancer cells." (PMID 38022639, 2023). "To delineate the functional relevance of Pax5 expression in NE-like cancer, we studied cell-cell interaction pathway." (PMID 38168280, 2023). "Overall, our results validate that Pax5 is preferentially expressed during the AR-independent NE-like cancer progression." (PMID 38168280, 2023). "Pax5 expression is highly specific to NE-like cancer, and depletion of Pax5 abrogates neuronal characteristics of t-NEPC." (PMID 38168280, 2023). "Larger cohort studies are required to investigate the penetrance for cancer in individuals with a germline PAX5 alteration." (PMID 37543654, 2023). "We link the transdifferentiation to a small subset of CSF1R+ Pax5Low cells within BM pre-B and immature B cells responding to cancer-secreted M-CSF with downregulation of the transcription factor Pax5 via CSF1R signaling." (PMID 36104343, 2022). "The human PAX5 gene locus is located on the 9p13 chromosomal region known to undergo a high degree of alterations leading to its implication in cancer development and progression." (PMID 36077495, 2022). "Several studies have revealed that PAX5 mainly functions as a transcriptional activator in various cancers." (PMID 36064939, 2022). "The expression profiles of various PAX5 products and their vast interacting networks ultimately determine the outcome of cell fate events and/or cancer processes." (PMID 36077495, 2022). "Amongst these members, PAX5 has been extensively studied and characterized for its role in cancer pathogenesis." (PMID 36077495, 2022). "Given that PAX5 is the key pro-B-cell factor that represses Csf1r and other myeloid lineage-specific genes, we reasoned that cancer decreases levels of this transcription factor using M-CSF." (PMID 36104343, 2022). "This phenomenon has been further substantiated by the demonstration that PAX5 methylation status directly correlates with overall survival rates of cancer patients." (PMID 36077495, 2022). "Given the importance of adequate methylation processes regulating PAX5-induced B-cell development, deregulated methylation results in the destabilization of B-cell homeostasis and cancer phenotypes." (PMID 36077495, 2022). "Disturbance of PAX5 spatial and temporal regulated expression ultimately leads to aberrant cellular processes and cancer." (PMID 36077495, 2022). "In the following sections, we will discuss the potential mechanisms of deregulated PAX5 expression in addition to the diversity of PAX5 products, which ultimately determine cellular function and cancer outcome." (PMID 36077495, 2022). "Our study not only brings new insight to the molecular biology of the post-transcription processing of Pax-5 mRNA but also provides new potential mechanisms for aberrant Pax-5 expression in cancer cells." (PMID 35011638, 2021). "We showed that cancer B-cells are characterized by a significant shortening of Pax-5 3′UTR regions in comparison to their healthy counterparts." (PMID 35011638, 2021). "Pax-5 3′UTR editing is thus a determining factor of miRNA-mediated regulation of the Pax-5 oncogene in cancer cells." (PMID 35011638, 2021). "Specifically, in mammary epithelial models, all Pax-5 3′UTRs from MCF7 cancer cells were truncated at 3.3 kb downstream of the stop codon, whereas 3′UTRs from MCF10A (non-cancerous) terminated at 3.9 kb." (PMID 35011638, 2021). "Altogether, our findings identify novel molecular mechanisms that account for aberrant expression and function of the Pax-5 oncogene in cancer cells." (PMID 35011638, 2021).
cancer (continued). "The Paired Box-5 (Pax-5) gene is a family of nuclear transcription factors, has been reported to be expressed in a variety of cancers, and is likely to contribute to overall tumorigenesis." (PMID 33952249, 2021). "We have previously reported that Pax-5 expression and function are modulated by key micro-RNAs (miRNAs) in various types of cancer cells." (PMID 35011638, 2021). "We demonstrate that the Pax-5 3′UTR is significantly edited in cancer cells through the use of APA or alternative splicing events, depending on the tissue type." (PMID 35011638, 2021). "Among the SNV top-ranked promoters (DMD), DHS elements (LRMP) and enhancers (PAX5, BACH2, BCL2, CXCR4, and BCL7A) are highly cancer-type-specific cases with many BCL or CLL mutations." (PMID 29354286, 2018). "PAX5 haploinsufficiency had the greatest influence on clusters involved in gene transcription, inflammatory and immune response, and cancer pathways." (PMID 28316978, 2017). "Both cancer tissues were positive for Pax-5 expression when compared to positive controls (B cells from FFPE tonsil samples)." (PMID 28076843, 2017). "Intriguingly, Pax-5 seems to confer an anti-proliferative effect in most carcinomas studied in opposition to its oncogenic effects in B cell cancers." (PMID 28076843, 2017). "At TFBS, hypermethylated DMRs were enriched for several TFs, most notable of which were the ligand activated and cancer-associated AHR, the development-associated PAX5 and cell cycle/cancer-related E2F family members." (PMID 25960784, 2015). "Another two TFs (PAX5 and SP1) are involved in cell differentiation, which also is a cancer-associated process." (PMID 21857930, 2011). "Similarly, miR-138 promotes MM cancer stem cell survival by repressing PAX5, a tumor suppressor transcription factor; its inhibition via antagomirs restores PAX5 expression, reducing clonogenicity and drug resistance." (PMID 41596492, 2026). "Therefore, Pax5 can be an early event of NE-like cancer and induce neuronal characteristics for the evasion of therapies." (PMID 38168280, 2023). "The enriched cancer-immune interactions in responding tumors are characterized by activation of the PAX5 module, a known regulator of B cell maturation, which colocalized with spots with increased B cell marker expression suggesting strong activity of these cells." (PMID 37723590, 2023). "For instance, PAX5 may trigger MET in circulating cancer cells thus implementing epithelial features essential for the establishment of distant metastatic colonization." (PMID 36077495, 2022). "PAX5 has also been reported to be part of a regulatory feedback loop with miR-155 in cancer cells." (PMID 36077495, 2022). "However, aberrant expression of PAX5 also consequently leads to pathological disorders, notably cancer." (PMID 36077495, 2022). "In addition, aberrantly expressed PAX5 contributed to the tumorigenesis and malignant progression of many other cancers." (PMID 33397394, 2021). "Given the oncogenic potency of Pax-5 products in B-cell malignancies, we hypothesized that aberrant overexpression of Pax-5 in these cancers may be due to 3′UTR shortening." (PMID 35011638, 2021). "In addition, genetic studies have shown that the human Pax-5 locus is involved in recurrent chromosomal rearrangements, which account for the aberrant expression of the Pax-5 oncogene in cancer." (PMID 35011638, 2021). "We thus generated a list of predicted miRNAs targeting the Pax-5 3′UTR in cancer cells." (PMID 35011638, 2021). "We hypothesized that down-regulated LTB (immune gene) modulated by PAX5 (TF) in STSs may have the capability of inducing cancer cell metastasis in patients with STS." (PMID 33397394, 2021). "Accordingly, our observation of extensive editing of Pax-5 3′UTRs in cancer cells may explain aberrant and oncogenic Pax-5 expression." (PMID 35011638, 2021).
cancer (continued). "We hypothesize that triggered expression of Pax-5 in circulating cancer cells would induce MET and concomitant suppression of mesenchymal gene expression." (PMID 28076843, 2017). "In other words, the phenotype transition triggered by Pax-5 may foster MET in circulating cancer cells enabling the establishment of distant metastatic niches." (PMID 28076843, 2017). "In contrast to B-cell cancer lesions, the specific role of Pax-5 in carcinoma development and progression is relatively unknown." (PMID 28076843, 2017). "The assortment of PAX5 products therefore complexifies our mechanistic elucidation of gene function and may account for the seemingly conflicting reports on PAX5 function in some cancer processes." (PMID 36077495, 2022). "However, Pax-5 deregulation is associated with various cancer lesions, notably hematopoietic cancers." (PMID 35011638, 2021). "However, we do not exclude the potential regulatory role of PAX5 in 7SK-associated genes in other types of cancer." (PMID 33868377, 2021). "Based on comprehensive bioinformatics analysis and preliminary experiments, we hypothesized that excessively downregulated LTB (an immune gene) modulated by PAX5 (a TF) in STSs induced cancer cell metastasis in patients with STS by modifying the haematopoietic cell lineage pathway." (PMID 33397394, 2021). "Consistent with the concept of oncogene addiction, in which secondary mutations are dependent upon driver mutations for maintaining the cancer phenotype, acquisition of additional mutations may therefore possibly render ALL cells even more vulnerable following replacement of PAX5 activity." (PMID 30216339, 2018). "However, it is important to note that the effects of Pax-5 on cancer progression would be time and context-dependent and that Pax-5 up-regulation during the initial (primary tumor) or later events could result in different pathological outcomes." (PMID 28076843, 2017). "Initially, we planned to test our approach with three crucial genes–PAX5, MYC, and CD79B –- known to play pivotal roles in cancer development and DLBCL growth." (PMID 39469218, 2024). "Based on our study, we concluded that continuous exposure to ARSI therapies leads to epigenetic modifications and Pax5 activation in t-NEPC, which promotes the expression of genes necessary to adopt taxane-resistant NE-like cancer." (PMID 38168280, 2023). "This study uncovers that PSMA3-AS1 functions as a cancer-promoting gene in CCA, and PAX5/PSMA3-AS1/miR-376a-3p/LAMC1 axis plays a vital role in CCA development." (PMID 35022330, 2022). "Our observations also presented significant differences in polymorphic patterns of Pax-5 3′UTRs from clinical samples in comparison to healthy donors (i.e., greater excised 3′UTR regions) where cancer cells possessed overall shorter 3′UTRs." (PMID 35011638, 2021). "As expected, splicing within the Pax-5 3′UTR was observed in all samples tested (i.e., 6 healthy donors and 17 cancer patients)." (PMID 35011638, 2021). "For instance, while MITF, SPDEF, CNOT7, BTK, PAF1, and PAX5 seem to be novel key regulators in the context of HPV-induced carcinogenesis, they are apparently already known to play essential roles in other cancer entities." (PMID 30918060, 2019).
cancer (continued). "Hypermethylation has already been reported for PAX5, KCNAB3, MEIS2 and GFRA3 in different cancer entities." (PMID 28634396, 2017). "In an analysis of 24 breast tumours, rearrangements were found in known cancer genes including BRAF, PAX3, PAX5, NSD1, PBX1, MSI2 and ETV6, each of which is a partner in a fusion gene in several other human cancers." (PMID 24792170, 2014). "Additionally, PAX5 had features in common with the consensus DEA, elastic net logistic regression, and canonical cancer genes in NCG." (PMID 40788820, 2025). "Our analysis validated that adenocarcinoma does not usually express Pax5, and cancer epithelial cells start expressing Pax5 only during NE-like transformation." (PMID 38168280, 2023). "Considering that the expression levels of WNK2, CYP1A1, PAX5, XRCC1, and TGM3 have been reported to be closely related to the development of cancer, we then detected the expression levels of these genes in SK-MES-1 and A549 cells after transfection of circFLNA and miR-486-3p mimic." (PMID 33500536, 2022). "For nearly two decades, the PAX5 gene has also been revealed to be an imperceptible regulator of cellular processes in various non-hematological tissues and cancers." (PMID 36077495, 2022). "Given the essential role of Pax-5 in B-cell maturation and cancer processes, we set out to clone, sequence, and map Pax-5 mRNA 3′UTR editing to gain a better understanding of post-transcriptional regulation leading to oncogenic Pax-5 expression." (PMID 35011638, 2021). "We hypothesize that this compound will have similar effects in other cancer cell types which also aberrantly express PAX proteins at a high level, particularly PAX2, and potentially PAX5, PAX6 or PAX8." (PMID 34722257, 2021). "We identified potential novel upstream regulators (e.g., CNOT7, SPDEF, MITF, and PAX5) controlling distinct clusters of genes within the HPV-host cell network as well as distinct factors (e.g., CPPED1, LCP1, and TAGLN) with essential functions in cancer." (PMID 30918060, 2019). "Even though there is no previous evidence in the literature for CCL7 abolishing immunoglobulin expression specifically during cancer progression, it was reported that MSC–derived CCL2 suppresses plasma cell immunoglobulin production via STAT3 inactivation and PAX5 induction." (PMID 30764543, 2019). "Using Spearman algorithms we were unable to demonstrate a correlation between Pax-5 expression and cancer pathology subtypes (data not shown)." (PMID 28076843, 2017). "In addition, of all the 31 Onco/TSGs harboured sHyperMethyl and sHypoMethyl in their gene body, 7 genes (HOXD11, TAL1, HOXA9, PAX5, FOXP1, FOXO1, TERT) were reported to serve as potential DNA methylation-based biomarkers for non-invasive early cancer diagnosis." (PMID 37393582, 2023). "In fact, PAX5 translocations are not well described in non-hematological cancer lesions." (PMID 36077495, 2022). "In addition, Aid is also reported to generate point mutations and/or double strand breaks at non-Ig locus, for example BCL6, MYC, PIM1 and PAX5, which are related to the cancer genesis." (PMID 24718089, 2014). "FACS staining confirmed that Pax5 was markedly decreased in BM CD93+ BMBP, particularly in CSF1R+ but not CSF1R− subsets, from mice with 4T1.2 or Mogp cancers." (PMID 36104343, 2022).
infection (24 papers, 2009 to 2025). The state of being infected such as from the introduction of a foreign agent such as serum, vaccine, antigenic substance or organism. "RNA sequencing further demonstrated that B-ALLs caused by loss of Pax5 grouped closely together (Sca1-ETV6-RUNX1 + Pax5-het mice and Pax5-het mice under infection exposure)." (PMID 34336858, 2021). "Susceptibility to infections in Pax5+/− mice was suggested to be due to a higher sensitivity of Pax5+/− pro-B cells to interleukin 7 (IL-7) withdrawal, favoring the accumulation of secondary Jak3 mutations as a rescue mechanism in these mice." (PMID 35004601, 2021). "By using flow cytometry and histology, we identified activated T cells that had developed from Pax5 deficient pro-B cells and responded to infection with the bacterial pathogen Listeria monocytogenes." (PMID 19340306, 2009). "Thus, the drivers of infection-associated B-ALLs are similar in both Pax5+/−;Myd88+/− and Pax5+/− leukemic cells." (PMID 37620322, 2023). "Incomplete penetrance seen in PAX5 mutated families is likely explained by the synergistic effects of these secondary or tertiary events, including environmental factors since, in heterozygous Pax5 mice, infection exposure mediated HM development." (PMID 37377909, 2023). "Nevertheless, it remained to be determined whether the mechanism driving B-ALL susceptibility in Pax5+/− mice under early exposure to infections was similar to the one driving B-ALL onset in Pax5+/− mice with delayed exposure." (PMID 37620322, 2023). "In the present study, we asked whether the inflammatory signals contribute to B-ALL development triggered by environmental infection exposure as a result of Pax5-inherited susceptibility." (PMID 33154497, 2020). "We recently showed that an inherited susceptibility to childhood pB-ALL (Pax5+/−) linked to a B-cell deficiency and followed by infection exposure may lead to pB-ALL." (PMID 29254279, 2017). "Furthermore, inherited Pax5 mutations are rare, hence we aimed to prove the theory of exposure to infection in pB-ALL development in a common subtype of pediatric pB-ALL such as ETV6-RUNX1 positive leukemia." (PMID 29254279, 2017). "Pdcd1fl/fl;Mb1-Cre;Pax5+/− mice were exposed to natural infections, and B-ALL development was monitored." (PMID 41283237, 2025). "We also observed that there is a proportionally greater frequency of CD1+ and Pax5+ B cells in the early immune response at day 14 of infection." (PMID 39494875, 2024). "Analysis of the TLR signaling pathway in preleukemic precursor B cells of Pax5+/− mice exposed to infections revealed a decrease in the expression of the adaptors Myd88 and Tirap, as well as the downstream transcription factor Nfkb1a." (PMID 37620322, 2023). "2-Dimensional hierarchical clustering of top DEGs in spleen samples (multi-group comparison) shows the key role of PAX5 in regulating infection resistance in Kashmiri favorella." (PMID 37098463, 2023). "We have shown that exposure to natural infections promotes full-blown B-ALL in Pax5+/− mice and that the malignant transformation of preleukemic precursor B-cells is associated with reduced levels of Myd88 expression." (PMID 37620322, 2023). "We generated Sca1-ETV6-RUNX1 + Pax5-het mice in an SPF environment to avoid the induction of second hits due to the exposure to infections." (PMID 34336858, 2021). "Especially two predisposed mouse models, Pax5+/− and Sca1-ETV6-RUNX1, highlighted the role of infections in the development of pB-ALL." (PMID 35004601, 2021). "Considering that Pax5-mutant preleukemic cells give rise to infection-triggered B-ALL in both human and mice, the relationship between inflammation and B-cell leukemogenesis is likely to be B-cell-dependent." (PMID 33154497, 2020). "Taken together, these data demonstrate that the decrease of IL-6 delays spontaneous formation of infection-driven B-ALL in Pax5+/- mice." (PMID 33154497, 2020).